PCSK9 (proprotein convertase subtilisin/kexin type 9)
Diseases named in the same sentence as PCSK9 in open-access papers (continued):
Sharing a sentence is not in itself a finding about the gene and the disease.
mood disorder (6 papers, 2020 to 2025). A cognitive disorder a disturbance in which the person's mood is hypothesized to be the main underlying feature. "The symptom onset following Repatha onset and the subsequent resolution upon discontinuation suggest a potential association between PCSK9 inhibition and mood disorders." (PMID 40755684, 2025). "Previously, we uncovered associations between genetic variants in the PCSK9 locus and mood disorder traits." (PMID 39325747, 2024). "The PCSK9 genetic locus has been recently implicated in mood disorders and hence we wanted to assess if the effect of PCSK9i that block the PCSK9 protein can lead to an increase in the incidence of mood disorders." (PMID 39325747, 2024). "Associations between PCSK9 protein levels and various mood disorder traits using two sample MR (IVW) test." (PMID 39325747, 2024). "However, this is a genetically proxied study using MR that estimates the lifetime causal effect of an exposure (in this case PCSK9 inhibition) with an outcome (in this case mood disorder traits)." (PMID 39325747, 2024). "In this study, we used genetically predicted protein levels of PCSK9 to proxy the pharmacological effect of PCSK9i, and MR analyses to explore the possibility that protein-targeting PCSK9i might increase the risk of mood disorder traits in the long-term." (PMID 39325747, 2024). "Specifically, we used genetic variants associated with reduced PCSK9 gene-expression (expression quantitative trait loci or eQTLs) to proxy the effects of PCSK9i (exposure) on mood disorder-related traits, circulating LDL levels, and PCSK9 protein levels (outcomes)." (PMID 36580462, 2022). "We investigated whether PCSK9 inhibition, proxied by a genetic reduction in expression of PCSK9 mRNA, might have a causal adverse effect on mood disorder-related traits." (PMID 36580462, 2022). "Although our previous study demonstrated an association between the PCSK9 locus and mood disorder-related traits, here we provide evidence that gene-expression modulation of USP24 –and not PCSK9 –is responsible for the causal effects on mood instability, and neuroticism scores." (PMID 36580462, 2022). "This is the first study to implicate the PCSK9 locus in mood-disorder symptoms and related traits, as well as the shared pathology of SMI and CMD." (PMID 35501368, 2022). "There is recent evidence of an association between PCSK9, both protein level and genetic variation in the PCSK9 locus, and mood disorders and related traits, including depressive symptoms and neuroticism." (PMID 36580462, 2022). "Whether the inhibition of PCSK9 could favor the onset of mood disorders was explored by Eudravigilance, the European centralized surveillance database for managing and analyzing reports of suspected adverse reactions to medications." (PMID 40755684, 2025). "We found that genetically reduced PCSK9 gene-expression levels were significantly associated with reduced PCSK9 protein levels but not with increased risk of mood disorder-related traits." (PMID 36580462, 2022). "In summary, here we have demonstrated that long-term use of PCSK9is, proxied genetically, which target PCSK9 protein levels are unlikely to increase the risk of mood disorder traits, consistent with our previous work using PCSK9 gene expression to mimic siRNA PCSK9is." (PMID 39325747, 2024). "PCSK9-expression is evident in non-hepatic tissues, notably the brain, and genetic variation in the PCSK9 locus has recently been shown to be associated with mood disorder-related traits." (PMID 36580462, 2022). "We can conclude that genetically proxied on-target effect of pharmacological PCSK9 inhibition is unlikely to contribute to mood disorders." (PMID 39325747, 2024). "Our results suggest that genetic variation in this region acts on mood disorders through a PCSK9-independent pathway, and therefore PCSK9-inhibitors are unlikely to have an adverse impact on mood disorder-related traits." (PMID 36580462, 2022).
mood disorder (continued). "The results for both our studies are consistent: long-term effect of PCSK9 inhibition, whether at the mRNA or the protein level, are unlikely to have a negative impact on mood-disorders." (PMID 39325747, 2024).
pancreatic cancer (6 papers, 2022 to 2025). "Furthermore, recent studies have shown that PCSK9 is directly implicated in the metastatic progression of both breast and pancreatic cancers." (PMID 40563628, 2025). "Although the role and expression characteristics of PCSK9 in various tumor cells have been well established, its specific expression profile in pancreatic cancer and its correlation with clinical prognosis remain inadequately elucidated." (PMID 39282119, 2024). "Regardless, it is an issue for future research to investigate the therapeutic potential of PCSK9 inhibitors in pancreatic cancer." (PMID 39282119, 2024). "Hence, we performed an observational cohort trial to identify the clinical utility of PCSK9 in pancreatic cancer in this context." (PMID 39282119, 2024). "Moreover, it was determined that in vitro and in vivo studies were required to confirm the biological activity of PCSK9 further and explore the relationship between PCSK9 and immunotherapy in pancreatic cancer." (PMID 39282119, 2024). "Our findings may implicate PCSK9 inhibition as a means for pancreatic cancer treatment." (PMID 37898598, 2023).
periodontitis (6 papers, 2012 to 2024). An acute or chronic inflammatory process that affects the tissues that surround and support the teeth. "Serum PCSK9 can potentially be used to screen for periodontitis and also evaluate the risk of developing CVD associated with periodontitis." (PMID 31015837, 2019). "However, the underlying mechanisms of elevation of PCSK9 in periodontitis patients are largely unknown." (PMID 22992388, 2012). "We have recently shown that serum levels of PCSK9 are significantly increased in periodontitis patients compared with periodontally healthy subjects." (PMID 22992388, 2012). "Plasma PCSK9 levels are elevated in patients with periodontitis, independently of LDL-C levels." (PMID 25180781, 2014). "A previous study by our group demonstrated that periodontitis, a chronic inflammatory disease induced by a group of periodontopathic bacteria, could elevate serum PCSK9 levels." (PMID 22992388, 2012). "Recently, we demonstrated that proprotein convertase subtilisin/kexin type 9 (PCSK9), which is known to play a critical role in the regulation of circulating low-density lipoprotein (LDL) cholesterol levels, is elevated in periodontitis patients." (PMID 22992388, 2012). "Nonetheless, some potential biomarkers were noticed in the serum of patients with periodontitis, such as resistin, C-reactive protein, visfatin, oncostatin M, chemokine CXCL10, and proprotein convertase subtilisin/kexin type 9 (PCSK9)." (PMID 37535199, 2023). "Moreover, the levels of serum proprotein convertase subtilisin/kexin type 9 (PCSK9) and total bilirubin, both of which exhibit positive or negative relationships with CVD, have been reported to increase or decrease in patients with periodontitis." (PMID 31015837, 2019).
ulcerative colitis (6 papers, 2022 to 2025). An inflammatory bowel disease involving the mucosal surface of the large intestine and rectum. "A previous study found that patients with active ulcerative colitis had higher serum PCSK9 levels than those with inactive disease." (PMID 41271978, 2025). "The SMR analysis showed no significant genetic association between increased gene expression of HMGCR, PCSK9, and NPC1L1 and IBD, Crohn’s disease (CD) and ulcerative colitis (UC)." (PMID 38191425, 2024). "There was no discernible difference in serum PCSK9, FC, and CE levels between patients with Crohn’s disease (CD) and those with ulcerative colitis (UC)." (PMID 40265438, 2025).
abetalipoproteinemia (5 papers, 2015 to 2022). "This group of diseases include Familial Hypobetalipoproteinemia (FHBL), Abetalipoproteinemia (ABL), Chylomicron Retention Disease and PCSK9 deficiency." (PMID 37138899, 2022). "Non-sense mutations in PCSK9 are also associated with low plasma levels of LDL-C and apoB, but in heterozygotes, the levels are not as low as in abetalipoproteinaemia and homozygous hypobetalipoproteinaemia and no systemic involvement is seen." (PMID 28124099, 2017).
acute kidney injury (5 papers, 2016 to 2025). Sudden and sustained deterioration of the kidney function characterized by decreased glomerular filtration rate, increased serum creatinine or oliguria. "Here, we describe a case of subacute CCE-induced acute kidney injury rescued with evolocumab, a novel proprotein convertase subtilisin/kexin type 9 (PCSK9) inhibitor." (PMID 41209160, 2025). "However, recent case reports have indicated new evidence regarding their association with acute kidney injury (AKI), with some patients experiencing acute tubular injury after PCSK9 inhibitors use." (PMID 39148544, 2024). "Proprotein convertase subtilisin/kexin type 9 (PCSK9) inhibitors have been shown to inhibit pyroptosis and apoptosis, which play important roles in the development and progression of contrast-induced acute kidney injury (CI-AKI)." (PMID 36051574, 2022). "This suggests that Pcsk9 gene expression and serum PCSK9 concentration are closely related to renal failure." (PMID 26481479, 2016).
age-related macular degeneration (5 papers, 2021 to 2026). Age-related loss of vision in the central portion of the retina (macula), secondary to retinal degeneration. "In its recent annual report, AIFA published aggregated reports for MP in some therapeutic areas of interest such as: chronic hepatitis C, age-related macular degeneration, family hypercholesterolemia (PCSK9) on the characteristics of the patients treated, and prescribing centers in the regions." (PMID 34456724, 2021).
aortic valve calcification (5 papers, 2022 to 2026). "Patients with the highest PCSK9 concentrations have the highest CAC score and a PCSK9 loss-of-function variant is protective for aortic valve calcification." (PMID 35600486, 2022). "The high interrelation between PCSK9 and aortic valve calcification has already been stressed." (PMID 36979039, 2023). "Subgroup analysis of the FOURIER study revealed that the PCSK9 inhibitors could decrease the incidence of calcific aortic valve disease." (PMID 35600486, 2022). "Furthermore, recent experimental studies have shown that PCSK9 could be involved in the process leading to aortic valve calcification and that the in vitro inhibition of PCSK9 could decrease VIC calcification." (PMID 35743402, 2022). "As a result, CD36 stabilizes and binds to proprotein convertase subtilisin/kexin type 9 (PCSK9), which ultimately accelerates the development and progression of aortic valve calcification." (PMID 39834390, 2024).
Arrhythmia (5 papers, 2019 to 2025). Any cardiac rhythm other than the normal sinus rhythm. "The arrhythmia score in the PCSK9 inhibitor pre‐treated group was significantly decreased when compared to the control group." (PMID 31557388, 2019). "Clinicians should remain alert for arrhythmias in high-risk patients beginning PCSK9 inhibitor therapy, but such isolated observations should not preclude treatment when cardiovascular benefits outweigh potential risks." (PMID 41404258, 2025). "Furthermore, in a preclinical study, pretreatment of rats undergoing I/R injury with a PCSK9 inhibitor decreased the arrhythmia score as well." (PMID 36675100, 2023). "In addition to the reduction in mitochondrial ROS, our results also clearly demonstrated that only the PCSK9 inhibitor pre‐treatment group had a lower arrhythmia score than the control group." (PMID 31557388, 2019). "However, administration of the PCSK9 inhibitor during ischaemia and at the onset of reperfusion did not reduce the arrhythmia score." (PMID 31557388, 2019).
cardiac arrest (5 papers, 2020 to 2025). Cessation of breathing and/or cardiac function. "In the primary analysis of seven trials, PCSK9 inhibitors therapy did not significantly reduce the risk of cardiac arrest (RR 1.20, 95%CI 0.61–2.33; P = 0.60; I2 = 0%)." (PMID 40779566, 2025). "PCSK9 inhibitor therapy did not significantly reduce the risk of SCD (RR 0.83, 95% CI 0.54–1.28; P = 0.40; I2 = 0%), ventricular arrhythmias (RR 0.81, 95% CI 0.60–1.09; P = 0.17; I2 = 0%), and cardiac arrest (RR 1.20, 95% CI 0.61–2.33; P = 0.60; I2 = 0%)." (PMID 40779566, 2025).
Crohn disease (5 papers, 2018 to 2025). A gastrointestinal disorder characterized by chronic inflammation involving all layers of the intestinal wall, noncaseating granulomas affecting the intestinal wall and regional lymph nodes, and transmural fibrosis. "For instance, PTVs in CARD9, RNF186 and IL23R provide protection against Crohn’s disease and/or ulcerative colitis and PTVs in ANGPTL4, PCSK9, LPA, and APOC3 protect against coronary heart disease." (PMID 29691392, 2018).
esophageal cancer (5 papers, 2021 to 2025). A primary or metastatic malignant neoplasm involving the esophagus. "Because the AUC showed the highest values for esophageal cancer among the solid tumors, we focused on the 91 surgical cases of esophageal cancer and examined the correlation between stages and s-PCSK9-Ab levels." (PMID 34504788, 2021). "Compared with patients with low s-PCSK9-Ab levels, those with high s-PCSK9-Ab levels had a favorable postoperative prognosis after radical surgery for esophageal cancer." (PMID 34504788, 2021). "Regarding esophageal cancer, patients with high s-PCSK9-Ab levels showed favorable prognosis compared with those with low s-PCSK9-Ab levels." (PMID 34504788, 2021). "This study has raised the possibility that anti-PCSK9 monoclonal antibody or PCSK9 vaccine is effective in improving the prognosis of low s-PCSK9-Ab patients with esophageal cancer." (PMID 34504788, 2021). "The reactivity of serum antibodies against recombinant PCSK9 protein was investigated by Western blotting, and the expression of PCSK9 antigens in esophageal cancer tissues was examined by immunohistochemical staining." (PMID 34504788, 2021). "High s-PCSK9-Ab levels indicated better prognosis for overall survival after surgery in patients with esophageal cancer." (PMID 34504788, 2021). "When the cutoff value was determined to be 542, the sensitivity and specificity of serum PCSK9-Abs for patients with esophageal cancer were 62.5% and 81.2%, respectively." (PMID 34504788, 2021). "Comparison of serum PCSK9 antibody levels according to clinicopathological characters of the patients with esophageal cancer." (PMID 34504788, 2021). "Moreover, patients with high s-PCSK9-Ab levels were found to have a favorable prognosis in the case of esophageal cancer." (PMID 34504788, 2021). "We observed a significantenrichment of PCSK6, PCSK9,MBTPS1, and FURIN mRNAs in the tumor tissue,which may be indication of the involvement of these PCs in the development andprogression of esophageal cancers." (PMID 40264581, 2025).
glioma (5 papers, 2022 to 2025). A benign or malignant brain and spinal cord tumor that arises from glial cells (astrocytes, oligodendrocytes, ependymal cells). "Genes associated with the neuronal differentiation pathway (Pcsk9, Runx1, Cebpb, Fzd4, Wnt7a, Ascl1, Fzd2, Edn3, Olig2, and Gpc2), gliomas (Shc1, Cdk4, E2f2, and Ccnd1), and cell cycle (Bub1b, Bub, Ccnb1, Ccnb2, and Cdc20) were significantly downregulated." (PMID 36147849, 2022). "PCSK9 gene silencing leads to cell shrinkage, loss of membrane integrity, nuclear fragmentation, and chromatin compaction, whereas PCSK9 overexpression in these glioma cells restores normal morphology." (PMID 37586604, 2023). "In contrast, PCSK9 displays anti-apoptotic properties in U251 human glioma cells." (PMID 37586604, 2023). "In the context of gliomas, PCSK-9 inhibition triggers the activation of caspase-3 and promotes apoptosis, while PCSK-9 overexpression suppresses apoptosis." (PMID 39813769, 2025). "Proprotein convertase subtilisin/kexin type 9 (PCSK9) promotes MHC-I degradation and is elevated in glioma." (PMID 41131134, 2025).
head and neck cancer (5 papers, 2021 to 2026). A primary or metastatic malignant neoplasm affecting the head and neck. "Beyond the liver, PCSK9 expression in multiple cancers, including colorectal, hepatocellular, and head and neck carcinomas, correlates with poor survival." (PMID 41767258, 2026). "Further investigation is required to untangle the relationship between PCSK9, alcohol and head and neck cancer, including a subsequent multivariable MR analysis." (PMID 33886544, 2021). "The mechanism of action of PCSK9 may be independent of cholesterol-lowering, however further replication of this finding in other head and neck cancer datasets is required." (PMID 33886544, 2021).
hyperthyroidism (5 papers, 2014 to 2024). Overactivity of the thyroid gland resulting in overproduction of thyroid hormone and increased metabolic rate. "Robust evidence was assigned to PCSK9 inhibition (OR = 0.85, 95% CI: 0.76, 0.96) and hyperthyroidism (increased susceptibility, OR = 0.86, 95% CI: 0.79, 0.94) with relatively small sample size." (PMID 38489391, 2024). "However, IVW-MR analyses did not demonstrate any significant link between genetically mimicry of PCSK9 inhibition and hyperthyroidism risk." (PMID 38425755, 2024). "Also consistent with the findings in hyperthyroidism, eprotirome treatment was associated with markedly reduced (−25%) levels of Lp(a) as well as PCSK9 (−17%)." (PMID 25172631, 2014). "Both hyperthyroidism and eprotirome treatment reduced circulating PCSK9, lipoprotein cholesterol, apoB and AI, and lipoprotein(a), while cholesterol synthesis was stable." (PMID 25172631, 2014). "TH-induced reductions in PCSK9 levels likely contributed to the lower LDL-C and Lp(a) levels in hyperthyroidism." (PMID 35606076, 2022). "It has been reported that patients with hyperthyroidism are shown lower serum levels of VLDL-, LDL-, and HDL-cholesterols, apolipoprotein B (apoB), lipoprotein-α (Lpα) and proproteinconvertasesubtilisin/kexin type 9 (PCSK9)." (PMID 29246135, 2017).